IVD (isovaleryl-CoA dehydrogenase)
Description:
A mitochondrial matrix enzyme that catalyzes the third step in leucine catabolism, where isovaleryl-CoA (3-methylbutanoyl-CoA) is metabolized to 3-methylbut-2-enoyl-CoA. To a lesser extent, it also participates in the first step in fatty acid beta-oxidation, in which it catalyzes the proR-proR stereospecific alpha,beta-dehydrogenation of other saturated short-chain acyl-CoA thioesters such as pentanoyl-CoA, hexanoyl-CoA and butanoyl-CoA, using the electron transfer flavoprotein (ETF) as their physiologic electron acceptor.
Synonyms: ACAD2; IVDH
Tractability: Small molecule: a structure with a bound ligand is known; it has a high-quality binding pocket. PROTAC: ubiquitination databases record sites on it; its protein half-life has been measured.
Gene: Protein-coding gene on chromosome 15 (40,405,485 to 40,435,947, forward strand). Ensembl gene ENSG00000128928.
Subcellular location: Mitochondrion matrix
Subcellular location (Human Protein Atlas): Mitochondria; Nucleoplasm
Pathways (Reactome):
Disease: Isovaleric acidemia
Metabolism: Branched-chain amino acid catabolism
Gene Ontology:
Molecular function: 3-methylbutanoyl-CoA dehydrogenase activity; protein binding; identical protein binding; acyl-CoA dehydrogenase activity; flavin adenine dinucleotide binding; medium-chain fatty acyl-CoA dehydrogenase activity; oxidoreductase activity, acting on the CH-CH group of donors; short-chain fatty acyl-CoA dehydrogenase activity
Biological process: branched-chain amino acid catabolic process; fatty acid beta-oxidation using acyl-CoA dehydrogenase; L-leucine catabolic process
Cellular component: mitochondrion; mitochondrial matrix
Genetic constraint (gnomAD): Loss-of-function variants: 31 observed, 53.9 expected, observed/expected ratio (o/e) 0.58, 90% interval 0.43 to 0.78. The upper end of that interval is the gene's LOEUF score, 0.78, which puts it in group 3 of 6, group 1 being the genes least tolerant of losing a copy. Missense variants: 475 observed, 584.06 expected, observed/expected ratio (o/e) 0.81, 90% interval 0.75 to 0.88. Synonymous variants: 205 observed, 232.69 expected, observed/expected ratio (o/e) 0.88, 90% interval 0.79 to 0.99.
Gene-disease validity (ClinGen):
ClinGen rates the evidence that IVD causes each of these diseases.
isovaleric acidemia (autosomal recessive): Definitive.
Homologues: Orthologues: chimpanzee IVD (99% identical), rabbit IVD (94% identical), guinea pig IVD (92% identical), rat Ivd (90% identical), mouse Ivd (89% identical), macaque IVD (89% identical), dog IVD (86% identical), pig IVD (84% identical), tropical clawed frog ivd (78% identical), zebrafish ivd (73% identical), Caenorhabditis elegans ivd-1 (62% identical), Drosophila melanogaster CG6638 (61% identical). Paralogues in human: ACADS (35% identical), ACAD9 (34% identical), ACADSB (32% identical), ACADL (31% identical), ACADM (31% identical), ACADVL (30% identical), GCDH (30% identical), ACAD8 (29% identical), ACAD11 (22% identical), ACAD10 (22% identical), ACOX1 (21% identical), ACOX3 (20% identical), and 2 more.
Diseases named in the same sentence as IVD in open-access papers:
IVD is named in the same sentence as 13 diseases in open-access papers, as found by Europe PMC text mining. Sharing a sentence is not in itself a finding about the gene and the disease. The quoted sentences say what the papers report.
isovaleric acidemia (10 papers, 2014 to 2025). "Isovaleric acidemia is a disorder of Leu catabolism due to deficient activity of isovaleryl-CoA dehydrogenase." (PMID 40428324, 2025). "Mutations in the IVD gene can result in isovaleric acidemia, a rare autosomal recessive disorder, that results in the buildup of isovaleric acid." (PMID 37839702, 2023). "Individual gene performances (using RWR) for this sign varied from best prediction (rank = 1) for IVD (isovaleryl-CoA dehydrogenase) causing isovaleric acidemia, to worst (rank = 7525) for GK (glycerol kinase) causing glycerol kinase deficiency." (PMID 28715999, 2017). "Isovaleric acidemia (IVA) is an autosomal recessive disease of leucine metabolism due to deficiency of isovaleryl-CoA Dehydrogenase (IVD)." (PMID 24637313, 2014). "In addition, isovaleric acidemia is an inborn error of leucine metabolism caused by a congenital deficiency of isovaleryl CoA dehydrogenase with elevated urinary IVA metabolites." (PMID 33768674, 2021). "Isovaleric acidemia (IVA) is an autosomal recessive disease of the leucine metabolism due to a deficiency of isovaleryl-CoA dehydrogenase (IVD)." (PMID 32257695, 2020). "Isovaleric acidemia is an autosomal recessive inborn error of leucine metabolism arising from a defect in the mitochondrial enzyme isovaleryl-CoA dehydrogenase, resulting in the accumulation of derivatives of isovaleryl-CoA, such as glycine conjugation and isovaleric acid." (PMID 39621302, 2024). "Isovaleric acidemia (IVA), an inborn error of leucine catabolism, is caused by mutations in the isovaleryl-CoA dehydrogenase (IVD) gene, resulting in the accumulation of derivatives of isovaleryl-CoA including isovaleryl (C5)-carnitine, the marker metabolite used for newborn screening (NBS)." (PMID 33072933, 2018). "Isovaleric acidemia (IVA, OMIM: 243500) is an autosomal recessive leucine inborn error of metabolism caused by the deficiency of mitochondrial isovaleryl-CoA dehydrogenase (IVD; EC 1.2.99.10), encoded by the IVD gene." (PMID 32977617, 2020).
metabolic acidosis (2 papers, 2024 to 2025). "IVA, encoded by the IVD gene, is classified into two diverse phenotypes: the acute neonatal form causes metabolic acidosis, leading to lethargy, vomiting, coma, or death, while the chronic form typically has a late onset in childhood with an asymptomatic phenotype." (PMID 38784038, 2024). "Our structural analysis of IVD mutations reveals that destabilization of FAD binding directly impairs enzymatic activity, which correlates with severe neonatal-onset IVA cases presenting with life-threatening metabolic acidosis." (PMID 40851894, 2025).
lung carcinoma (1 paper, 2021). "SLC25A42, AMT, and IVD genes have also been found in other prognostic models of lung cancer." (PMID 34539973, 2021). "In addition, our model screened several genes that have not been studied in the field of lung cancer but are closely related to the prognosis of LUAD patients, such as SLC25A42, AMT, and IVD, which provides a basis for future research on the mechanism of lung cancer." (PMID 34539973, 2021).
organic acidemias (1 paper, 2021). "With the suspicion of organic acidemias early in her life, the coding regions and splicing sites of GCDH, ETFA, ETFB, ETFDH, IVD were evaluated by PCR and sequencing and no pathogenic variant was identified." (PMID 35083005, 2021).
tumor (2 papers, 2023 to 2025). "Under normal physiological conditions, isovaleryl-CoA is oxidized by isovaleryl-CoA dehydrogenase (IVD) to 3-methylcrotonyl-CoA, entering β-oxidation and ketogenesis to yield acetyl-CoA, thereby fueling energy production and biosynthetic processes that sustain tumor growth." (PMID 41145761, 2025). "However, when IVD activity is compromised (e.g., due to genetic defects or mitochondrial dysfunction), isovaleryl-CoA accumulates and is diverted toward conjugation with carnitine, forming isovalerylcarnitine (C5), which we identify as a novel tumor suppressor in GC." (PMID 41145761, 2025). "Four genes increased concordantly in EGFR-amplified tumours in both primary and recurrent samples: EEA1 (co-localising early endosomal antigen 1 with the EGFR–EGF complex as it enters intracellularly), IVD (isovaleryl-coA dehydrogenase), SEC61G (co-expressed with EGFR on chr 7p11), and EGFR itself." (PMID 36765632, 2023).
cancer (1 paper, 2017). A tumor composed of atypical neoplastic, often pleomorphic cells that invade other tissues. "Betaine–homocysteine S-methyltransferase 1 (BHMT), isovaleryl-CoA dehydrogenase (IVD), short-chain specific acyl-CoA dehydrogenase (CRAT) and arginase-1 were all down-regulated in cancer tissues of HCC without PVT and further deceased in the cancer tissues of HCC with PVT." (PMID 28785178, 2017).
IVD also shares sentences with these, for which no sentence is quoted: bacterial infections (1 paper); breast carcinoma (1); carnitine deficiency (1); Hypoglycemia (1); ischemia (1); metabolic disease (1); Stroke (1).